BLOC1S1 (biogenesis of lysosomal organelles complex 1 subunit 1)
Description:
Component of the BLOC-1 complex, a complex that is required for normal biogenesis of lysosome-related organelles (LRO), such as platelet dense granules and melanosomes. In concert with the AP-3 complex, the BLOC-1 complex is required to target membrane protein cargos into vesicles assembled at cell bodies for delivery into neurites and nerve terminals. The BLOC-1 complex, in association with SNARE proteins, is also proposed to be involved in neurite extension. As part of the BORC complex may play a role in lysosomes movement and localization at the cell periphery. Associated with the cytosolic face of lysosomes, the BORC complex may recruit ARL8B and couple lysosomes to microtubule plus-end-directed kinesin motor. Acts as a protein acetyltransferase. Negatively regulates aerobic respiration through mitochondrial protein lysine-acetylation. May counteract the action of the deacetylase SIRT3 by acetylating and regulating proteins of the mitochondrial respiratory chain including ATP5F1A and NDUFA9. Acts as a regulator of mTORC2 signaling in response to hypotoxic stress by mediating acetylation of RICTOR, thereby protecting RICTOR against ubiquitination and subsequent degradation by the proteasome.
Synonyms: BLOS1; GCN5L1; RT14; BORCS1; MICoA
Tractability: PROTAC: ubiquitination databases record sites on it; its protein half-life has been measured.
Gene: Protein-coding gene on chromosome 12 (55,716,033 to 55,720,087, forward strand). Ensembl gene ENSG00000135441.
Subcellular location: Mitochondrion intermembrane space; Mitochondrion matrix; Cytoplasm, cytosol; Lysosome membrane
Pathways (Reactome):
Vesicle-mediated transport: Golgi Associated Vesicle Biogenesis; Lysosome Vesicle Biogenesis
Gene Ontology:
Molecular function: protein binding; protein-lysine-acetyltransferase activity
Biological process: aerobic respiration; lysosome localization; anterograde axonal transport; anterograde synaptic vesicle transport; endosomal transport; melanosome organization; neuron projection development; organelle transport along microtubule; platelet dense granule organization; regulation of endosome size; regulation of lysosome size
Cellular component: BLOC-1 complex; BORC complex; cytosol; extracellular region; mitochondrial intermembrane space; mitochondrial matrix; cytoplasmic side of lysosomal membrane; lysosomal membrane; axon cytoplasm; early endosome
Genetic constraint (gnomAD): Loss-of-function variants: 11 observed, 18.73 expected, observed/expected ratio (o/e) 0.59, 90% interval 0.37 to 0.97. The upper end of that interval is the gene's LOEUF score, 0.97, which puts it in group 4 of 6, group 1 being the genes least tolerant of losing a copy. Missense variants: 220 observed, 201.19 expected, observed/expected ratio (o/e) 1.09, 90% interval 0.98 to 1.22. Synonymous variants: 94 observed, 78.82 expected, observed/expected ratio (o/e) 1.19, 90% interval 1.01 to 1.42.
Homologues: Orthologues: pig BLOC1S1 (82% identical), mouse Bloc1s1 (81% identical), dog BLOC1S1 (80% identical), zebrafish bloc1s1 (73% identical), rabbit BLOC1S1 (71% identical), tropical clawed frog bloc1s1 (67% identical), Drosophila melanogaster Blos1 (45% identical), Caenorhabditis elegans blos-1 (42% identical).
Diseases named in the same sentence as BLOC1S1 in open-access papers:
BLOC1S1 is named in the same sentence as 51 diseases in open-access papers, as found by Europe PMC text mining. Sharing a sentence is not in itself a finding about the gene and the disease. The quoted sentences say what the papers report.
hepatocellular carcinoma (5 papers, 2022 to 2025). A malignant tumor that arises from hepatocytes. "For instance, BLOC1S1 has been associated with mitochondrial dysfunction and metabolic regulation in hepatocellular carcinoma, where it plays a role in oxidative phosphorylation and cellular metabolism." (PMID 40370519, 2025).
breast carcinoma (3 papers, 2023). "Despite the p-values for AUCs of some genes such as AP3B2, BLOC1S1, NUDT13, PTCH1, and ZNF609 being statistically significant in all three breast cancer subtypes, their significance in HER2+ cancers and TNBC were much lower compared to that in ER+/HER2- breast cancer patients." (PMID 37700842, 2023).
myeloma (3 papers, 2015 to 2022). "Lentiviral transduction of myeloma cells with BLOC1S1 constructs was successful, as observed by an increase in total BLOC1S1 transcript to at least double that for untransduced cells and a measurable expression of qTag." (PMID 25870107, 2015). "DTT treatment induced degradation of WT BLOC1S1 but not G444C BLOC1S1 in myeloma cells, as observed by a decrease in total BLOC1S1 and qTag expression in WT-transduced cells and an increase in BLOC1S1 and qTag expression relative to GAPDH in G444C-transduced cells." (PMID 25870107, 2015).
Sepsis (3 papers, 2022 to 2025). Sepsis is defined as life-threatening organ dysfunction caused by a dysregulated host response to infection. "Previous studies identified BLOC1S1 as a critical gene associated with sepsis outcomes, consistent with its role in this study." (PMID 40370519, 2025). "Clinically, BLOC1S1, NDUFA1, and SFT2D1—have also been implicated in various disease contexts beyond sepsis." (PMID 40370519, 2025). "In adult sepsis, BLOC1S1, ROMO1, SLIRP and TIMM8B showed excellent ability to identify nonsurvivor samples." (PMID 37249456, 2023). "Finally, ANKRD22, GPR84, GYG1, BLOC1S1, CARD11, NOG, and LRG1 were recognized as critical genes associated with sepsis molecular subtypes." (PMID 36035194, 2022). "Among them, BLOC1S1 showed the strongest positive correlation with activated dendritic cells (cor = 0.577, P < 0.001), suggesting that BLOC1S1 might be involved in the regulation of activated dendritic cell processes, thereby affecting the immune response in sepsis." (PMID 40370519, 2025). "This study identified BLOC1S1, NDUFA1, and SFT2D1 as histone acetylation-related biomarkers for sepsis and validated their expression in THP-1 cell models and patient blood samples." (PMID 40370519, 2025). "Macrophage differentiation trajectories revealed increased expression of BLOC1S1 and NDUFA1 during later stages of sepsis, suggesting their involvement in immune cell reprogramming." (PMID 40370519, 2025). "This study identified three histone acetylation-related genes, BLOC1S1, NDUFA1, and SFT2D1, as potential biomarkers for sepsis through integrated bioinformatics analysis." (PMID 40370519, 2025). "In GSE154918 and GSE69063 datasets, ANKRD22, GPR84, GYG1, BLOC1S1, and LRG1 were all highly expressed in sepsis patients, whereas NOG and CARD11 were dramatically decreased in sepsis patients." (PMID 36035194, 2022). "Furthermore, validation using patient blood samples confirmed the elevated expression levels of BLOC1S1, NDUFA1, and SFT2D1 in sepsis patients compared to healthy controls." (PMID 40370519, 2025). "Additionally, the “toll-like receptor signaling pathway” was activated in BLOC1S1 and SFT2D1, which might indicate a key regulatory mechanism of the inflammatory response in sepsis." (PMID 40370519, 2025). "There are remarkable differences in ANKRD22, GPR84, GYG1, BLOC1S1, CARD11, NOG, and LRG1 gene expression and enriched pathways among different molecular subgroups of sepsis, which may be the key factors leading to the heterogeneity of clinical symptoms and prognosis in patients with sepsis." (PMID 36035194, 2022). "Furthermore, some mitGenes with a concordant expression gain related to ATP production mechanism were shared between hypothyroidism and sepsis: SLIRP and TIMM8B appeared in sepsis nonsurvivor scenarios; ROMO1 and BLOC1S1 were present in both survivor and nonsurvivor scenarios." (PMID 37249456, 2023). "Concurrently, BLOC1S1 exhibited the strongest negative correlation with central memory CD4+ T cells (cor = −0.761, P < 0.001), indicating that BLOC1S1 might suppress the function or quantity of central memory CD4+ T cells, playing a complex role in the immunological dysregulation of sepsis." (PMID 40370519, 2025).
asthma (2 papers, 2018). "Similar inflammation mechanisms could explain why two genes (C2 and BLOC1S1) previously associated with age-related macular degeneration might also be implicated in asthma as shown here." (PMID 30096133, 2018).
brucellosis (2 papers, 2022 to 2025). Brucellosis is a bacterial infection that spreads from animals to people via unpasteurized dairy products or by exposure to contaminated animal products or infected animals. "Here, we show that Brucella, the causative agent of brucellosis, the most prevalent bacterial zoonosis globally, subverts this immune defense pathway by activating regulated IRE1α-dependent decay (RIDD) of Bloc1s1 mRNA encoding BLOS1, a protein that promotes endosome–lysosome fusion." (PMID 35587649, 2022).
atopic dermatitis (1 paper, 2024). "At the same time, it is interesting that transcriptomic analysis in 16 atopic dermatitis subjects, shows that BLOC1S1 expression is significantly blunted in association with this allergic ichthyosis." (PMID 39803487, 2024).
polyglucosan body myopathy (1 paper, 2022). "GYG1 deficiency is known to be associated with polyglucosan body myopathy and BLOC1S1 is widely recognized as a degradation substrate for IRE1alpha." (PMID 36035194, 2022).
sarcoidosis (1 paper, 2022). Sarcoidosis is a multisystemic disorder of unknown cause characterized by the formation of immune granulomas in involved organs. "Some dysregulated genes discovered in our meta-analysis have not been found to be associated with sarcoidosis previously, but variations of these genes such as CCNB1, BLOC1S1, and KIF1B are associated to some extent with fibrotic diseases, including complication of sarcoidosis and tuberculosis." (PMID 36203777, 2022).
ZIKV infection (1 paper, 2025). "To determine activation of the IRE1 endonuclease activity through the RIDD branch during ZIKV infection in human microglia, we measured expression of canonical RIDD targets Bloc1s1, Scara3, and Per1." (PMID 41157563, 2025).
cancer (5 papers, 2015 to 2023). A tumor composed of atypical neoplastic, often pleomorphic cells that invade other tissues. "Using cancer cell lines, we show that BLOC1S1 is specifically cleaved by IRE1 at guanine 444, but only under conditions of IRE1 hyperactivation." (PMID 25870107, 2015). "Cleavage of BLOC1S1 occurred more slowly than XBP1 splicing, and the cleavage of BLOC1S1, or RIDD as a whole, was dispensable for the control of cancer cell viability under acute ER stress." (PMID 25870107, 2015).
infection (5 papers, 2022 to 2025). The state of being infected such as from the introduction of a foreign agent such as serum, vaccine, antigenic substance or organism. "Second, we used real-time quantitative reverse transcription-PCR (qRT-PCR) to measure the expression levels of several candidate RIDD genes, including Bloc1s1, Cd300lf, Diras2, and Txnip during infection." (PMID 35587649, 2022). "However, based on prior evidence of BLOC1S1 downregulation at 24 h post‐infection, we selected 24 h for subsequent assays." (PMID 40936170, 2025). "Expression levels of Bloc1s1 mRNA were dramatically reduced during infection." (PMID 35587649, 2022). "Host cells harboring nonfunctional Bloc1s1 mutants were highly susceptible to pathogen infection, whereas cells that express a RIDD-resistant Bloc1s1 variant were resistant to Brucella infection." (PMID 35587649, 2022). "The RIDD-resistant Bloc1s1 variant maintains the integrity of BORC and a higher-level association of BORC-related components that promote centrifugal lysosome trafficking, resulting in enhanced BCV peripheral trafficking and lysosomal destruction, and resistance to infection." (PMID 35587649, 2022). "Inactivation of the Bloc1s1 gene impaired the ability to assemble BLOC-1-related complex (BORC), resulting in differential recruitment of BORC-related lysosome trafficking components, perinuclear trafficking of Brucella-containing vacuoles (BCVs), and enhanced susceptibility to infection." (PMID 35587649, 2022). "(H) qRT-PCR analysis of expression levels of Bloc1s1 in ΔXbp1 BMDMs that were either uninfected (control), infected with Bm16M, or treated with tunicamycin (Tm, an UPR inducer, 5 μg/ml) at 4-hr post infection/treatment." (PMID 35587649, 2022). "However, BLOC1S1, SCARA3, COL6A1, and HGSNAT were unaffected by HCoV-OC43, suggesting that IRE1α activity is limited to XBP1 splicing during infection." (PMID 37306512, 2023).
tumor (5 papers, 2022 to 2025). "Furthermore, differential analysis of tumor cells in the two single-cell datasets (high CDI vs. low CDI) found that all genes from the lysosome-dependent cell death gene set (BLOC1S1, AP1S2) were stable in both datasets." (PMID 39773329, 2025).
BLOC1S1 also shares sentences with these, for which no sentence is quoted: hyperglycaemia (2 papers); Hypertension (2); iron deficiency (2); liver cancer (2); ovarian carcinoma (2); schizophrenia (2); acute kidney injury (1); age-related macular degeneration (1); albinism (1); Allergy (1); autism (1); bacterial infections (1); cardiac ischemia (1); COVID-19 (1); diabetes (1); diabetic kidney disease (1); endothelial dysfunction (1); fibrosis (1); Huntington disease (1); hyperlipidaemia (1); hypertrophy (1); hypothyroidism (1); Insulin resistance (1); ischemic stroke (1); kidney damage (1); multiple myeloma (1); Myocardial fibrosis (1); neurological diseases (1); nonalcoholic steatohepatitis (1); overnutrition (1).
A further 8 diseases each share a sentence with BLOC1S1 in 1 paper.